IFNG (interferon gamma)
Diseases named in the same sentence as IFNG in open-access papers (continued):
Sharing a sentence is not in itself a finding about the gene and the disease.
tuberculosis (continued). "Based on search criteria for manuscripts reporting tuberculosis susceptibility and its relationship with the IFNG +874 T/A(rs2430561)polymorphism, 42 case-control studies from 39 different articles were retrieved." (PMID 28881572, 2017). "Further studies with larger sample sizes and consideration of gene-environment interactions should be conducted to elucidate the role of IFNG +874 T/A(rs2430561) polymorphism in tuberculosis susceptibility." (PMID 28881572, 2017). "In other studies, the A allele of IFNG +874 had also been shown to influence the outcome of diseases such as parvovirus and tuberculosis." (PMID 29531550, 2017). "We performed an updated meta-analysis to evaluate the association between the IFNG +874 T/A (rs2430561) polymorphism and tuberculosis susceptibility." (PMID 28881572, 2017). "Polymorphisms in genes for the Toll-like receptor (TLR), interleukin (IL), vitamin D receptor (VDR) and interferon-gamma (IFN-γ) are associated with susceptibility to tuberculosis." (PMID 28693442, 2017). "Currently, the gene encoding interferon-γ (IFNG) is the most extensively studied gene regarding tuberculosis susceptibility." (PMID 28881572, 2017). "Although interferon-gamma, interleukin-10, and adiponectin are key immunopathogenesis mediators of tuberculosis, their association with clinical manifestations of early stage disease is inconclusive." (PMID 26880909, 2016). "The most widely used ante-mortem diagnostic tests for tuberculosis in cattle are the tuberculin skin test and the interferon-gamma (IFN-γ) release assay, both of which measure cell-mediated immune responses to Mycobacterium bovis infection." (PMID 27167122, 2016). "To address these uncertainties, we determined the incidence rates of active tuberculosis disease in a cohort of high-risk immigrants with Class B TB screened with interferon-gamma release assays (IGRAs) upon arrival in the United States." (PMID 27558397, 2016). "IFNG plays a role in infectious disease pathogenesis where polymorphisms have been shown to increase risk for infectious diseases including tuberculosis, malaria, and Chagas disease." (PMID 25479081, 2014). "IFNG, in particular, is essential for protective immunity to tuberculosis, and individuals who carried a genetic deficiency in the receptor for IFNG were more likely to succumb to mycobacterial infection." (PMID 24505407, 2014). "miR-29 was able to block increased IFNγ levels, a typical feature of general miRNA knockout mice, and over-expression of miR-29 increased susceptibility to tuberculosis." (PMID 26567102, 2014). "The importance of IFNγ and IL-12 in protection against disease was evident from the increased risk of tuberculosis in individuals with deficiencies in either the IFNγ or IL-12 signaling pathways." (PMID 23544075, 2013). "A key factor for susceptibility against tuberculosis is IFNγ and the underlying TH1 immune response." (PMID 23613882, 2013). "Although no correlate of protection to tuberculosis has been identified, the ability to generate IFNγ-producing T-cells has been shown to be important, as defects in IFNγ signalling lead to a high susceptibility to tuberculosis disease." (PMID 22243970, 2012). "A receiver operating curve (ROC) was generated to calculate the diagnostic accuracy of sputum PPD-specific IFNγ for diagnosis of active tuberculosis." (PMID 22778764, 2012). "The second largest IFNG-vaccine-VO network contains the small network and also genes and interactions associated with specific VO vaccine terms or their synonyms (e.g., tuberculosis vaccine BCG)." (PMID 21624163, 2011). "Interferon gamma is a major macrophage-activating cytokine during infection with Mycobacterium tuberculosis, the causative pathogen of tuberculosis, and its role has been well established in animal models and in humans." (PMID 20525402, 2010). "IFNγ polymorphism (+874 Thi→Alo) is the most studied polymorphism in terms of association with tuberculosis disease sites and severity." (PMID 19274101, 2009).
tuberculosis (continued). "Single nucleotide polymorphisms (SNPs) located in the first intron of the IFNγ gene (at position +874) have shown variable associations with tuberculosis disease susceptibility and severity." (PMID 19274101, 2009). "The diagnostic utility of HBHA-based interferon gamma release assays (IGRAs) has been further evaluated in Belgium, a country with low tuberculosis (TB) incidence where bacille Calmette et Guérin (BCG) vaccinations are rarely used." (PMID 18815611, 2008). "An additional IFNG SNP was obtained from the literature, rs2430561, with a reported association with tuberculosis." (PMID 16504056, 2006). "Baricitinib, a selective JAK1 and JAK2 inhibitor, may predispose to tuberculosis by suppressing interferon-gamma (IFN-γ)-mediated signaling, which is essential for macrophage activation and granuloma maintenance." (PMID 40735451, 2025). "This study evaluated whether fetal bovine serum (FBS) supplementation can preserve the diagnostic performance of the interferon-gamma release assay (IGRA) for bovine tuberculosis under delayed testing conditions." (PMID 40941374, 2025). "Interferon gamma release assay, routine passive and active case detection, portable X-ray and nucleic acid amplification testing, and highly sensitive enzyme-linked immunosorbent assay tests play critical roles in improving tuberculosis detection." (PMID 38965640, 2024). "Additionally, upon reexposure to mycobacterial antigens, lymphocytes from individuals infected with tuberculosis release higher levels of IFN-γ, suggesting interferon-gamma as a potential diagnostic marker for tuberculosis infection." (PMID 39445216, 2024). "Given the crucial role of IFNG in the protection against Mtb infection, these results are in line with the genetic association found between the C carriers of the rs763780 SNP and the susceptibility to tuberculosis." (PMID 31616423, 2019). "In order to get further evidences that support the protective role of the A allele in developing tuberculosis, IFNG levels in plasma and IFNG production by Mtb-Ag-stimulated PBMCs from HD carrying the different genotypes of the IFNG rs1861494 SNP were determined by ELISA and Flow Cytometry." (PMID 29361774, 2018). "Also, the logistic regression used to evaluate the association between the IFNG rs1861494 SNP and tuberculosis disease was adjusted for age, ethnicity and sex." (PMID 29361774, 2018). "Here, by using a case-control study, we reported an association between the AA and AG genotype of the IFNG rs1861494 SNP with tuberculosis resistance in Argentina, indicating that only one copy of the A allele is enough to confer protection against the disease in our population." (PMID 29361774, 2018). "Also, CMV- and EBV-directed IFNγ production in peripheral blood has been linked to better survival among patients with tuberculosis (characterized by chronic inflammation) after successful completion of standard antibiotic therapy." (PMID 29970101, 2018). "Considering the important role of IFNG+874 T/A (rs2430561) polymorphism in TB development, we studied all eligible case-control studies that included characteristics such as ethnicity of the patients, types of tuberculosis, and control sources." (PMID 28881572, 2017). "Our meta-analysis suggests that the IFNG +874 T/A(rs2430561)polymorphism is potentially associated with tuberculosis susceptibility and may be used as a predictive biomarker." (PMID 28881572, 2017). "Indeed, recent studies have shown thatchronic filarial infection is associated with decreased PPD-specific IFNγ and IL-17responses in individuals latently infected with tuberculosis." (PMID 23285308, 2012). "In particular, functional/putatively functional SNPs in genes that affect macrophage anti-mycobacterial activity (e.g., vitamin D receptor [VDR], monocyte chemoattractant protein [MCP–1], and interferon [IFNγ]) associate with increased risk for and severity of tuberculosis in various ethnic groups." (PMID 21339808, 2011).
tuberculosis (continued). "Based on the hypothesis that genes which regulate interferon gamma may influence tuberculosis susceptibility, we investigated polymorphisms in eight candidate genes." (PMID 20525402, 2010). "Taken together our results clearly demonstrate that HHCs are a population at high risk of infection and disease development and show a marked difference in the risk of tuberculosis development depending on the levels of IFNγ production in response to CFP-10 shortly after exposure to M. tuberculosis." (PMID 20011589, 2009). "Herein we present evidence that levels of IFNγ response to CFP-10 assessed shortly after exposure to an infectious source may be predictive of tuberculosis development in a population of HHCs at high risk of infection." (PMID 20011589, 2009). "PPD and the tuberculosis (TB) interferon-gamma (IFN-γ) release assay (TB-IGRA) are both associated with mycobacteria, and have a relatively high sensitivity and specificity for the diagnosis of ITB, especially TB-IGRA." (PMID 35110611, 2022). "As with other intracellular pathogens, protective immune responses against tuberculosis (TB) are associated with interferon gamma (IFN-γ) production derived from T helper 1 (TH1) CD4 T cells." (PMID 34336973, 2021). "The only current tests that can identify those at risk of TB are interferon gamma release assays (IGRAs) or TSTs, which detect immunological sensitization to M. tuberculosis." (PMID 30990820, 2019). "Therefore, our data suggest that the A allele of the IFNG rs1861494 SNP could be considered as a biomarker for tuberculosis resistance in Argentina." (PMID 29361774, 2018). "Interferon-gamma release assays (IGRAs) have been used to identify individuals at risk for developing active tuberculosis (TB)." (PMID 25938227, 2015). "The aim of the study was to assess the correlation between the tuberculin skin test (TST) and in vitro interferon-gamma released assays (IGRAs) with risk factors for the spread of infection in smear positive pulmonary tuberculosis (TB) contacts." (PMID 24885850, 2014). "Cigarette smoking is known to increase the risk of tuberculosis (TB) and to impair Interferon-gamma (IFN-γ) responses to antigenic challenge, but the impact of smoking on IGRA performance is not known." (PMID 23270417, 2012). "Immunity to TB is associated with the accumulation of IFNγ-producing T helper cell type 1 (Th1) in the lungs, activation of M.tuberculosis-infected macrophages and control of bacterial growth." (PMID 21249199, 2011). "TB proteins encoded by the RD-1 gene of Mycobacterium tuberculosis (M. tuberculosis) are used in commercially available IGRA (Interferon-gamma Release Assays) blood tests [QuantiFERON®-TB Gold In-tube, (QFT-TB) and T spot-TB®]." (PMID 18366633, 2008). "Tuberculosis screening showed positive tuberculin skin test (12 mm) and positive interferon-gamma release assay, with normal chest radiography." (PMID 41908889, 2026). "The interferon-gamma release assay (IGRA) has low sensitivity in detecting tuberculosis in patients with HIV." (PMID 40026931, 2025). "It is recommended that tuberculosis screening be enhanced through a combination of interferon-gamma release assay and tuberculin skin test, with needle biopsy employed when necessary to improve diagnostic accuracy and prevent misdiagnosis." (PMID 41473162, 2025). "A positive interferon-gamma release assay (IGRA) prompted evaluation for active tuberculosis, including chest radiography, thoracoabdominopelvic computed tomography, and cervical ultrasound, all of which yielded normal findings." (PMID 40673288, 2025). "Subsequently, the diagnostic algorithm for TB (chest X-ray, repeated microbial sputum samples, and interferon gamma test), as recommended by the German S2k guideline on the treatment of tuberculosis in adults, was performed." (PMID 40025616, 2025). "An active Tuberculosis (TBC) disease was excluded using both the Interferon gamma-release assays (IGRAs)—the T-SPOT.TB and QuantiFERON-TBgoldPlus tests." (PMID 41562657, 2025).
tuberculosis (continued). "As an example, the interferon gamma release assay (IGRA) is already used for the diagnosis of patients with tuberculosis." (PMID 40109344, 2025). "Sarcoidosis tends to be bilateral and systemic with elevated ACE levels, whereas tuberculosis often presents with basal meningeal enhancement and positive interferon-gamma release assays (IGRAs)." (PMID 40985429, 2025). "CXCL10, induced by interferon-gamma (IFN-gamma), is integral to the immune response against tuberculosis, as it aids in the recruitment of immune cells to the infection site and contributes to granuloma formation—a hallmark of TB pathology." (PMID 40164948, 2025). "An ischemic stroke and the detection of tuberculosis, indicated by increased interferon-gamma, each occurred in a single patient, respectively." (PMID 41258942, 2025). "The tuberculosis-specific interferon gamma test was positive and thus confirmed the patient’s previous contact with Mycobacterium tuberculosis." (PMID 40025616, 2025). "A study that explored blood cells and interferon-gamma level correlation in LTBI recruited 88 household contacts of tuberculosis pulmonary patients and compared blood cells." (PMID 40559721, 2025). "Nonspecific endoscopic findings, widespread lymphadenopathy, and an indeterminate result from the tuberculosis interferon-gamma release assay (TB-IGRA) raised suspicion for tuberculosis or lymphoma." (PMID 41189221, 2025). "Radiographic findings such as miliary patterns on chest imaging and positive interferon-gamma release assays or cultures will distinguish tuberculosis from CRS." (PMID 40277755, 2025). "Previous studies contained data on the sensitivity of tuberculin skin tests or interferon gamma release assays (IGRAs) for Mycobacterium tuberculosis (M. tuberculosis) infection in different forms of tuberculosis." (PMID 40137824, 2025). "T-SPOT.TB is a type of ELISpot assay used for tuberculosis diagnosis, which belongs to the group of interferon-gamma release assays." (PMID 38771503, 2024). "Major changes in the full blood count and liver and kidney function impairment must be excluded before starting therapy, as well as the Tuberculosis interferon gamma release assay (TB-IGRA)." (PMID 39518448, 2024). "For instance, the interpretation of interferon-gamma (IFN-gamma) for bovine tuberculosis or polymerase chain reaction cycle threshold (PCR Ct) values for blue tongue requires laboratory expertise in addition to epidemiological knowledge." (PMID 39234170, 2024). "The CD patients with MAP infection in the TU/ACU study had elevated (IFNγ), TNFα and IL-17A like tuberculosis patients, but they did not have elevated IL-2, IL-5, IL-10 and GM-CSF typically reported in tuberculosis patients." (PMID 38415011, 2024). "The patient underwent emergency pericardiocentesis, and the pericardial fluid interferon-gamma assay result was positive for tuberculosis." (PMID 38872689, 2024). "This analysis revealed their involvement in critical processes such as the innate immune response to tuberculosis, interferon-gamma signaling, and the NOD-like receptor signaling pathway." (PMID 38935691, 2024). "Here, a proteome-wide screen of 20,610 Mtb-derived peptides in 21 patients mid-treatment for active tuberculosis (ATB) reveals IFNγ-specific T cell responses against 137 unique epitopes." (PMID 38278794, 2024). "The panel we employed included cytokines that are elevated in tuberculosis, i.e., interferon gamma (IFNγ), IL-2, IL-5, IL-10, IL-17, GM-CSF and TNFα." (PMID 38415011, 2024). "Latent tuberculosis (TB) testing with interferon-gamma release assay was serially indeterminate, so the pulmonary team was consulted for bronchoscopy and bronchoalveolar lavage." (PMID 39130976, 2024). "The patient was diagnosed with sarcoidosis and suspected latent tuberculosis (as suggested by a positive tuberculin test and tuberculosis interferon-gamma release assays) and received prednisone under follow-up." (PMID 38022146, 2023).